CISD1 (CDGSH iron sulfur domain 1)
Diseases named in the same sentence as CISD1 in open-access papers (continued):
Sharing a sentence is not in itself a finding about the gene and the disease.
cancer (continued). "Copy number alterations were the most common genomic change in most of the cancers, and cancers with higher rates of CISD1 amplifications had a higher expression level of CISD1, which further confirms that CISD1 is an oncogene in multiple cancers." (PMID 40831536, 2025). "The development of novel therapeutics targeting CISD1's iron-sulfur cluster or modulating its protein expression holds great potential for improving cancer outcomes." (PMID 40831536, 2025). "Building on the success of pioglitazone, novel compounds have been developed to target CISD1 in cancer." (PMID 40831536, 2025). "Our results are also consistent with previous reports that CISD1 is a prognostic biomarker in several cancers." (PMID 40831536, 2025). "This pan-cancer approach highlights the universal and specific roles of CISD1, supporting its candidacy as a robust biomarker for predicting cancer outcomes and tailoring immunotherapy strategies." (PMID 40831536, 2025). "Despite these limitations, our integrative analysis provides valuable insights into the potential roles of CISD1 in cancer biology and identifies it as a promising biomarker and therapeutic target." (PMID 40831536, 2025). "Taken together, these results highlight the potential importance of CISD1 in cancer progression and treatment, particularly in the context of the immune response and tumor microenvironment." (PMID 40831536, 2025). "We first downloaded the CISD1-positive coexpression genes in these five cancers from cBioPortal, and performed Venn analysis using SangerBox online tools, and found that there were 26 overlapped genes in the five cancers analyzed." (PMID 40831536, 2025). "Our analysis is consistent with previous studies that have showed CISD1 is up-regulated in several cancers." (PMID 40831536, 2025). "In this study, we found that expression levels of CISD1 were dramatically dysregulated in various cancers." (PMID 40831536, 2025). "This systematic pan-cancer analysis lays a strong foundation for further exploring the biological functions of CISD1 in cancers." (PMID 40831536, 2025). "The comprehensive analyses presented in this study establish the significance of CISD1 in cancer and its potential value as a multi-biomarker for improving cancer prognosis and treatment." (PMID 40831536, 2025). "Given the heterogeneity of cancer and the need for robust biomarkers across cancers, this study conducts the first comprehensive pan-cancer analysis of CISD1 by evaluating its roles in cancer and treatment." (PMID 40831536, 2025). "Our pan-cancer analysis highlights CISD1 as not only a reliable biomarker but also a highly promising anti-cancer target due to its overexpression in multiple cancer types." (PMID 40831536, 2025). "We also used GEPIA 2.0 online tools to generate survival heatmaps and Kaplan–Meier survival curves to reveal the relationship between CISD1 expression and overall survival across various cancer types." (PMID 40831536, 2025). "Elevated levels of CISD1 in specific cancers indicate its possible oncogenic role in tumor growth, and oncogenes play multiple, interconnected roles in cancer progression by driving cell proliferation and promoting metastasis." (PMID 40831536, 2025). "The role of CISD1 is even more important in cancers, as cancer cells often exhibit alterations in mitochondrial function to support rapid proliferation and resistance to apoptosis." (PMID 40831536, 2025). "Our results indicate that CISD1 expression correlates with patient prognosis and immune cell infiltration in various cancers." (PMID 40831536, 2025). "Given its associations with immune cell infiltration and immunotherapy response, CISD1 can be explored as a potential therapeutic target and/or a biomarker for predicting treatment outcomes in cancer patients." (PMID 40831536, 2025). "Taken together, these results reveal significant variations in CISD1 expression, with most cancers showing elevated levels." (PMID 40831536, 2025).
cancer (continued). "Taken together, the significant associations between CISD1 expression and patient outcomes strongly suggest that CISD1 can be a potential prognostic biomarker for multiple cancers." (PMID 40831536, 2025). "Our study revealed that CISD1 was significantly and positively correlated with stemness indices in multiple cancers, indicating that CISD1 is involved in promoting or maintaining stem cell-like properties in cancer cells." (PMID 40831536, 2025). "Our pan-cancer analysis further confirms that CISD1 is significantly overexpressed in various cancer types, conferring a survival advantage to cancer cells." (PMID 40831536, 2025). "This reproducible and significant correlation between CISD1 expression and patient survival across various cancers strengthens its use as a prognostic biomarker in clinical settings." (PMID 40831536, 2025). "Using cBioPortal, CISD1 showed mutation frequency in several cancers, in which UCEC (>1%) had the highest rate of CISD1 gene mutations frequency, followed by STAD, SARC, LIHC, SKCM, OV, and LUAD." (PMID 40831536, 2025). "CISD1 mediates mitochondrial lipid peroxidation to inhibit ferroptosis, which plays an important role in promoting cancer cell proliferation and supporting tumor development and metastasis." (PMID 37072786, 2023). "Previous findings have consistently shown that CISD1 negatively regulated ferroptosis by protection against mitochondrial lipid peroxidation in Cancer." (PMID 36843917, 2023). "Among them, CISD1 was also found to be closely linked to CLEC12B, CLEC2B and CSTA in a variety of cancers, with CLEC2B being involved in the largest number of cancer types." (PMID 36030279, 2022). "Another study showed that the ferroptosis-related gene CISD1 is anticipated to become one of the novel biomarkers for predicting the prognosis of breast cancer patients, thereby providing a new target for cancer therapy." (PMID 36406272, 2022). "The impact of CISD1 expression on survival rates was analyzed using TCGA pan-cancer expression and clinical data by the univariate Cox regression analysis and Kaplan-Meier analysis." (PMID 35313629, 2022). "The mRNA expression of CISD1 in multiple cancers and tumor-adjacent normal tissues was analyzed using TCGA database data to detect the difference in expression of CISD1 in tumor and normal tissue." (PMID 35313629, 2022). "Recent studies revealed that the CISD1 plays a critical role in promoting the proliferation of cancer cells, supporting tumor growth and metastasis." (PMID 35313629, 2022). "Knock-down CISD1 can significantly inhibit cancer cells proliferation and reduce uncontrolled reactive oxygen and iron accumulation." (PMID 36671422, 2022). "Pan-cancer analysis was performed to determine the expression profile and prognostic value of CISD1 in human cancers." (PMID 35313629, 2022). "In order to identify the difference of CISD1 expression between tumors and normal tissues, first, a pan-cancer analysis was performed to identify CISD1 expression level among 33 cancers data deposited in TCGA." (PMID 36671422, 2022). "After investigating the pan-cancer section of ENCORI, an online tool, CISD1 was discovered to be highly linked to CLEC2B, CLEC12B and CSTA in a variety of cancer types." (PMID 36030279, 2022). "Among the genes corresponding to DNA methylation in the prognostic signature, we identified that ZEB1 and DUOX1 are drivers of ferroptosis and that CISD1 is a suppressor of ferroptosis, which play a crucial role in cancer development." (PMID 36555319, 2022). "The differential expression of CISD1 between cancer and normal tissues was observed in many types of cancers." (PMID 35313629, 2022). "CISD1, also known as mitoNEET, is instrumental for the proliferation, migration, and invasion of tumor cells and accelerates the occurrence of malignant tumors." (PMID 36203872, 2022).
cancer (continued). "Specifically, CISD1 (CDGSH iron sulfur domain 1, CISD1—also known as mitoNEET) performs a key role in in promoting the proliferation of cancer cells and tumor growth." (PMID 36671422, 2022). "A recent study revealed that the NEET protein CISD1 plays a critical role in promoting the proliferation of cancer cells, supporting tumor growth and metastasis." (PMID 34249899, 2021). "Our further explorations indicated that MTX1 interacts with CISD1 by Co-IP assays, whereas CISD1 functions as an autophagy repressor in cancer." (PMID 34421355, 2021). "For example, heat shock protein beta-1 (HSPB1) and CDGSH iron sulfur domain 1 (CISD1) are both negative regulators of ferroptotic cancer cell death." (PMID 33537073, 2021). "The function of CISD1 in cancer cells was found to be dependent on the degree of lability of their 2Fe-2S clusters, whereas the mechanism of CISD1 in LUAD remained unclear." (PMID 34249899, 2021). "Second, CISD1 can be a prognostic biomarker for cancer patients." (PMID 40831536, 2025). "This study is the first comprehensive pan-cancer bioinformatics analysis to determine the functions of CISD1 in multiple cancers using public patient databases, and demonstrate that CISD1 is a potential diagnostic, prognostic and immunotherapeutic biomarker for multiple cancers." (PMID 40831536, 2025). "Indeed, CISD1 has emerged as the mitochondrial target of thiazolidinedione drugs such as the antidiabetic pioglitazone, suggesting the potential therapeutic value of SB-T-101141 for CISD1-positive cancers." (PMID 40389408, 2025). "Furthermore, CISD1's expression in some cancers was negatively correlated with tumor indices, RNA modification enzymes, immune cell infiltration, or immune checkpoint proteins." (PMID 40831536, 2025). "Our study showed that 26 genes are coexpressed with CISD1 across five types of cancer that have high expression levels of CISD1, high stemness signatures, high levels of RNA modifications, and worse patient survival, and 20 of them are highly expressed across a wide range of cancers." (PMID 40831536, 2025). "Thus, increased expression of CISD1 can be used to predict response to immune checkpoint inhibitors in cancers." (PMID 40831536, 2025). "Although CISD1 has been identified as a prognostic biomarker in specific cancers, its broader implications in tumorigenesis, cancer progression, and immunotherapy remain unclear." (PMID 40831536, 2025). "Next, we wondered if the protein expression level of CISD1 was also increased in various cancers." (PMID 40831536, 2025). "We next used SangerBox online tools to analyze the correlation between CISD1 mRNA expression and RNA modification enzymes that catalyze m1A, m5C, and m6A, as these RNA modifications play critical roles in cancer by regulating gene expression, mRNA stability, translation, and tumor progression." (PMID 40831536, 2025). "Our study validated that CISD1 could be a reliable biomarker for cancer prognosis, as patients with higher expression levels of CISD1 had a lower survival probability from the overall survival analysis in multiple cancers." (PMID 40831536, 2025). "We next analyzed the genetic profile of CISD1 in cancer tissues." (PMID 40831536, 2025). "Up-regulation of CISD1 was reported in various cancer types, and CISD1 was shown to play crucial roles in tumor progression, resistance to apoptosis, and poor prognosis, making it an interesting topic of research in understanding carcinogenesis and developing therapeutic strategies." (PMID 40831536, 2025). "Combined with the regulation of CISD1 protein on iron and ROS metabolism in mitochondria and the high expression level of CISD1 protein in different tumors, CISD1 protein may play a key role in cancer cell proliferation." (PMID 35313629, 2022). "We investigated the prognostic value of CISD1 in human cancers." (PMID 35313629, 2022). "Pan-cancer analysis of TCGA data showed that CISD1 is differentially expressed in multiple tumors." (PMID 35313629, 2022).
cancer (continued). "CISD1 protein contents were higher than normal tissues in 20 cancer types." (PMID 36671422, 2022). "Next, CISD1 expression level were evaluated and varied in different cancer types." (PMID 36671422, 2022). "In our prognostic model of LUAD, we surprisingly found that ACSL3 and CISD1 were promoters of ferroptosis, whereas the remaining three genes were suppressors of ferroptosis, which was opposite of the results acquired in other cancers." (PMID 34115610, 2021). "CISD1 (mitoNEET), an iron-containing outer mitochondrial membrane protein, negatively regulates ferroptosis cancer cell death, and promotes the proliferation of cancer cells, adjuvant tumor growth and metastasis." (PMID 33947836, 2021). "Taken together, these results suggest that CISD1 coexpression genes are involved in vital biological processes, particularly related to cellular energy production and metabolic processes, and likely play significant roles in cancer cell survival and proliferation." (PMID 40831536, 2025). "Targeting CISD1 in cancers with high stemness signatures may offer a promising therapeutic avenue." (PMID 40831536, 2025). "Taken together, these results suggest that CISD1 may be associated with a more active immune response and potentially better outcomes in those positive correlation cancers, which makes CISD1 a potential marker of immunogenic tumors that may respond well to immunotherapy." (PMID 40831536, 2025). "In addition to CISD1 up-regulation in the vast majority of cancers analyzed, we observed that CISD1 expression was down-regulated in six types of cancer, suggesting that it may play a different role in these cancers, potentially acting as a tumor suppressor." (PMID 40831536, 2025). "Thus, patients with high CISD1 expression may benefit from checkpoint inhibitor therapies in these cancers." (PMID 40831536, 2025). "Thus, we compared survival in cancer patients with high or low CISD1 expression levels." (PMID 40831536, 2025). "Moreover, cancer patients with significantly altered expression of CISD1 have lower survival rates and worse prognoses, and its expression is significantly correlated with tumor stemness indices in multiple cancers, highlighting its importance prognostic prediction as a crucial prognostic biomarker." (PMID 40831536, 2025). "These research findings demonstrate that CISD1, CISD2, and CISD3 have the potential to modulate ferroptotic cell death in cancer cells through the regulation of their ISCs." (PMID 37345031, 2023). "Based on function, the 12 FRGs can be grouped into four classes: Lipid metabolism (GPX4, LPCAT3, ACSL5, and ACSL6), antioxidant metabolism (CD44, SESN2, and AIFM2), iron metabolism (CISD1 and HSPB1), and cancer metabolism (SOCS1, FH, and G3BP1)." (PMID 34784264, 2022). "The findings revealed an exclusive correlation between CISD1 (ferroptosis regulator) and CLEC2B (hub gene) in PsA group as well as multiple cancer types." (PMID 36030279, 2022). "The 12 FRGs are divided into 4 categories according to their functions: lipid metabolism (GPX4, LPCAT3, ACSL5, ACSL6), antioxidant (CD44, SESN2, AIFM2), iron metabolism (CISD1, HSPB1), and cancer metabolism (SOCS1, FH, G3BP1)." (PMID 35559049, 2022). "CISD1 (CDGSH iron sulfur domain), an iron-containing outer mitochondrial membrane protein, negatively regulates ferroptotic cancer cell death." (PMID 33672990, 2021). "It is noteworthy that the ferroptosis suppressor genes, SLC3A2, FANCD2, CISD1, and ACSL3, were upregulated in most cancer types, indicating that ferroptosis was generally inhibited in cancers." (PMID 34434214, 2021). "In conclusion, previous studies have reported that PHKG2, PEBP1 and NCOA4 are positive regulators that promote ferroptosis in some kinds of cancers, whereas the remaining two genes (ACSL3 and CISD1) suppress ferroptosis in cells." (PMID 34115610, 2021).
cancer (continued). "Male patients showed higher mRNA expression levels of CISD1 in LUAD, HNSC, while female patients showed higher mRNA expression levels of CISD1 in KIPAN and KIRC, suggesting that its expression pattern in cancer has limited gender preference." (PMID 40831536, 2025). "A dual role of CISD1 in cancer is not unusual, as many genes exhibit context-dependent functionality." (PMID 40831536, 2025). "GEPIA2.0 online analysis of TCGA datasets showed that mRNA levels of CISD1 were significantly up-regulated in 22 of 33 total cancer types analyzed; and the following THPA analysis showed that protein expression levels of CISD1 were also significantly increased in multiple cancers." (PMID 40831536, 2025). "CISD1 also showed significant positive correlation with MSI in DLBC, HNSC, STAD, LIHC, STES, and GBMLGG, suggesting that patients with high CISD1 expression are more likely to benefit from immunotherapies in these cancers." (PMID 40831536, 2025). "Moreover, we found that TPD52, TF, and CCT6A were more frequently heterozygous amplified while STC2, CISD1, and P4HA2 were more likely to occur in heterozygous deletion in cancers." (PMID 36998462, 2023). "Although levels of CISD1 mRNA are significantly increased in different human cancer cells, the expression of CISD1 in HCC and its role are still not fully elucidated." (PMID 35313629, 2022). "In contrast, CISD1 might be involved in immune evasion and tumor progression in those negative correlation cancers, which makes CISD1 a potential target for enhancing immune infiltration and improving the effectiveness of cancer treatments." (PMID 40831536, 2025). "Indeed, CISD1 is significantly positively correlated with TMB and MSI in several cancers, indicating that patients with high expression of CISD1, together with high TMB and MSI, can benefit from immunotherapy, as a high TMB or MSI has been linked to better response to immune checkpoint inhibitors." (PMID 40831536, 2025). "Unfortunately, whether CISD1 has a marked effect on the prognosis of malignant tumors has not been reported." (PMID 36203872, 2022). "In contrast, CISD1 showed a significant negative correlation with MSI in LUAD, CESC, and PRAD, suggesting that patients with high CISD1 expression are less likely to respond to immunotherapies in these cancers." (PMID 40831536, 2025).